CD4 (CD4 molecule)
Diseases named in the same sentence as CD4 in open-access papers (continued):
Sharing a sentence is not in itself a finding about the gene and the disease.
Sepsis (continued). "Our findings revealed significant decreases in CD4, CD3e, IL-7R, CD5, CD247, CD2, CD40LG, ITK, and KLRB1, and significant elevations in MMP9, LCN2, and RETN in sepsis-induced ARDS compared to controls." (PMID 37822934, 2023). "The results showed the expression level of CD3D, CD3E, CD4, CD28, IL7R, and LCK was statistically different between sepsis and normal groups." (PMID 37113759, 2023). "A comparison of Sepsis tissues and normal tissues revealed that Sepsis tissues contained significantly fewer naïve B cells, memory naïve B cells, CD8 naïve T Cells, and CD4 naïve T Cells." (PMID 37007944, 2023). "In sepsis and burn patients, monocytes, macrophages, neutrophils and NKT cells were increased, whereas NK cells, CD4+ T cells and CD8+ T cells were decreased." (PMID 37060578, 2023). "We found that IL-10-secreting B cells are present in patients with sepsis-induced ARDS and had a higher percentage than other PBMC cells (including DCs, monocytes, and CD4+/CD8+ T cells)." (PMID 37443161, 2023). "CYT107 acts to enhance host immunity by restoring both the number and function of CD4+ and CD8+ T cells that are massively depleted in patients with sepsis and that play a critical role in host defenses against microbial pathogens." (PMID 36906875, 2023). "Mechanistically, EVs derived from LPS-treated CD4+ T cells carrying DGKK induced oxidative stress and inflammation in alveolar epithelial A549 cells and sepsis-induced mice through PKC and NOX4, the downstream effectors of DGKK and DAG." (PMID 36959535, 2023). "In sepsis and burn patients, monocytes, macrophages, neutrophils and NKT cells were significantly increased, while NK, CD4_T, CD8_T, gamma_delta, iTreg, Tfh, cytotoxic, exhausted, central_memory and effector_memory cells were significantly decreased." (PMID 37060578, 2023). "EVs derived from lipopolysaccharide (LPS)-treated CD4+ T cells carrying DGKK induced oxidative stress and inflammation in alveolar epithelial A549 cells and sepsis-induced mice through PKC and NOX4, the downstream effectors of DGKK and DAG." (PMID 36959535, 2023). "Clinical observation studies have indicated that patients with sepsis exhibit a decrease in peripheral blood CD3+T, CD4+T, and CD4+/CD8+T cell ratios, which are related to the severity of the disease." (PMID 37939116, 2023). "Previous research showed that in sepsis, CIRP adheres to the TLR4/MD2 complex on CD8 + and CD4 + T-cells, resulting in their activation and the production of TNFα and HMGB1 from APCs." (PMID 36920542, 2023). "We also found that the expression level of CD3D, CD3E, CD4, CD28, IL7R, and LCK was statistically different between sepsis and normal groups, indicating their potential role in the development of sepsis." (PMID 37113759, 2023). "guessed the initial low CD4, CD3, CD8 counts would have been due ongoing sepsis and after the infection is controlled the counts improved." (PMID 37469600, 2023). "However, the roles of CD4+ T-cell-derived EVs in sepsis-induced lung injury remain unknown." (PMID 36959535, 2023). "Subsequently, we identified module and hub genes (CD4 and STAT4) via construction of a sepsis immune-related PPI network." (PMID 37620751, 2023). "In contrast to CD3+CD4+ T cells, the percentage of CD3+CD8+ T cells decreased significantly from 24 hours (P< 0,05) and up to 5 days of sepsis development (P<0,01), as was observed after abdominal surgery patients." (PMID 38094297, 2023). "We aim to summarize and analyze the early characteristics of CD3+, CD4+, and CD8+ T lymphocyte counts, CD4+/CD8+ ratio changes in sepsis patients, and their correlations with short-term prognosis and long-term survival rates." (PMID 38170088, 2023). "CTLA-4 is also highly expressed in CD4 T cells, CD8 T cells, and/or inhibitory receptors in monocytes from patients with sepsis." (PMID 38114466, 2023).
Sepsis (continued). "This study aimed to investigate the early detection of CD3+, CD4+, and CD8+T-cell subsets in adult sepsis patients admitted to ICU and conducted a detailed analysis of both short-term and long-term prognostic indicators." (PMID 38170088, 2023). "The lower expression of the six hub genes (CD28, CD3D, CD4, IL7R, LCK, and CD3E) was observed in sepsis samples." (PMID 37113759, 2023). "Once gated in CD127-/low P2X7 receptor-expressing cells in sepsis, we observed that P2X7 receptor expression increased even in more than 50% of CD4++CD25+CD127-/low cells." (PMID 38094297, 2023). "Human sPD-1 level is positively correlated with the expression of PD-1 in CD4+ or CD8+T cells and the severity of sepsis." (PMID 37292207, 2023). "In the early stage of sepsis, most patients showed a decrease in CD3+, CD4+, and CD8+T-cell subsets, as well as in the CD4+/CD8+ ratio." (PMID 38170088, 2023). "miR‐126‐5p expression was negatively correlated with IL‐6, CRP, and PCT but positively correlated with IgA, IgM, and IgG as well as CD3+, CD4+, and CD8+ in patients with sepsis‐induced ALI." (PMID 37248197, 2023). "The lower expression of the hub genes (CD3D, CD3E, CD4, CD28, IL7R and LCK) was observed in sepsis samples, which was consistent in all the six hub genes." (PMID 37113759, 2023). "In a clinically relevant animal model of sepsis, CYT107 administration resulted in decreased CD4+ and CD8+ T-cell apoptosis." (PMID 37109229, 2023). "In mice with sepsis, LC3II/I expression in CD4 + T cells was significantly higher compared with that of control mice." (PMID 35435531, 2022). "In summary, it was found that compared with patients with G+ sepsis, patients with G- sepsis exhibited a higher percentage of CD3+CD8+CD69+T cells and a noticeably lower CD3+CD4+CD69+T/CD3+CD8+CD69+T ratio." (PMID 36703970, 2022). "With regard to adaptive immunity, our analysis indicated that CD4+ T cells, CD8+ T cells, T cells follicular helper, and B cells were all down-regulated in patients with sepsis, except regulatory T cells regulatory (Tregs)." (PMID 35844488, 2022). "Previous studies have found that in the pathogenesis of sepsis, T cell activation continues to fail, and the occurrence of sepsis is closely related to the failure of CD8+ helper T cell (Th)-1 and CD4+ Th17 lymphocytes." (PMID 36237524, 2022). "In terms of metabolism and cell activation, expression of mTOR on CD4+ and CD8+ T cells in the sepsis group was significantly higher than that in the non-sepsis group." (PMID 35898496, 2022). "We developed a mouse model of sepsis through cecal ligation and puncture (CLP) to investigate dynamic changes in autophagy in CD4 + T cells." (PMID 35435531, 2022). "Communication signals from CD4+ and CD8+T cells were suppressed comparing septic shock versus sepsis." (PMID 36304125, 2022). "The expression of CTLA-4 on CD4+ T cells in patients with sepsis is significantly increased, suggesting that CTLA-4 is a potential target for sepsis treatment." (PMID 36209190, 2022). "Although several biomarkers are routinely used in clinical practice, including mHLA-DR, circulating IL-10, and CD4+/CD8+ ratio, the validity of many others is solely manifested in the pre-clinical studies using an experimental model of sepsis." (PMID 35619710, 2022). "GM-CSF treatment in sepsis patients significantly decreased MDSCs and FOXP3+ Tregs but increased CD4 T-cell functionality and improved survival." (PMID 35720398, 2022). "The blood glucose level of patients with sepsis was positively correlated with the levels of IL-6, TNF-α, and IL-1β and was negatively correlated with the levels of CD4+/CD8+." (PMID 35664433, 2022). "Our results suggest that Nrp‐1 is beneficial for TGF‐β1 to enhance the stability of CD4+CD25+ Tregs, and may represent a novel therapeutic target with the potential to improve the CD4+CD25+ Tregs‐related primary negative immunoregulation associated with the TGF‐β1/Smads signaling pathway in sepsis." (PMID 34758202, 2022).
Sepsis (continued). "In G- sepsis (versus G+ sepsis), we observed that both CD3+CD69+T and CD3+CD8+CD69+T (%) were remarkably upregulated, while CD4+T/CD8+T ratio, CD3+CD4+CD69+T (%) and CD3+CD4+T were downregulated (although the latter two indexes without significant difference)." (PMID 36703970, 2022). "According to the results, Nrp‐1 mediates TGF‐β1 to improve the stability of regulatory CD4+CD25+ T cells and maybe a possible therapeutic target with the ability to improve the CD4+CD25+ Tregs associated negative immunoregulation that is related to the TGF‐β1/Smads cell signaling during sepsis." (PMID 34758202, 2022). "Our initial characterization of the T cell compartment revealed a notable increase of the CD4+ and CD8+ T cell number in the BM early after induction of sepsis." (PMID 36148245, 2022). "Together with endotoxin tolerance, massive cellular apoptosis of CD4+ and CD8+ T cells and immune exhaustion of T lymphocytes are typical of sepsis-induced immunosuppression." (PMID 35054993, 2022). "CD4+ and CD8+ T cells, B cells, natural killer cells and dendritic cells are especially depleted in sepsis." (PMID 36470832, 2022). "Patients with severe sepsis and T2DM had similar T cell PD-1+ CD4+ and T cell PD-1+ CD8+ expression and mortality rates in patients with only severe sepsis." (PMID 36010357, 2022). "The results showed that IL-7 treatment does not cause excessive inflammatory reactions or aggravate organ dysfunction but significantly increases CD4+ and CD8+ T lymphocyte counts in patients with sepsis." (PMID 36209190, 2022). "We found that ROS accumulation in sepsis led to ERS occurrence and that the mTOR pathway operating downstream of ERS induced CD4+ T cell apoptosis." (PMID 35915740, 2022). "Our results clearly suggested the benefit of GM-CSF therapy in sepsis patients, as it decreases the MDSCs, FOXP3 expression on CD4+ T cells, and the percentage of apoptotic T cells and increases CD4 T-cell proliferation." (PMID 35720398, 2022). "By constructing a mouse sepsis model, we next investigated the relationship between sepsis, ERS, and CD4+ T apoptosis." (PMID 35915740, 2022). "Our study shows a decrease in both CD4 and CD8 T cells and monocytes but an increase in circulating neutrophils, MDSCs, and Tregs in DC patients with sepsis." (PMID 35720398, 2022). "The disturbance of immune cells, including a drastic depletion of CD4 and CD8 lymphocytes, occurs in sepsis patients." (PMID 33997001, 2021). "Immunohistological staining revealed extensive depletion of splenic CD4, CD8 and HLA-DR cells in sepsis patients as compared with controls." (PMID 34945111, 2021). "We estimated the percentage and number of T lymphocytes (CD3+ CD19-), CD4+ T lymphocytes (CD3+ CD19- CD4+), CD8+ T lymphocytes (CD3+ CD19- CD8+), and the CD4+/CD8+ T lymphocyte ratio in two sepsis mouse models using flow cytometry." (PMID 33717146, 2021). "IL-7 is noted to increase CD4+ and CD8+ T cell numbers in murine sepsis by upregulating the expression of the anti-apoptosis regulator B-cell lymphoma 2 protein, which is associated with improved survival." (PMID 33920518, 2021). "exhibited that in the peripheral blood from ICU patients with sepsis, the proportion of BTLA expressing CD4+ T cells increased." (PMID 34163466, 2021). "Compared to sepsis-induced intrapulmonary ALI, higher serum levels of IL-38 were reported in sepsis-induced extrapulmonary ALI due to the high ratio of CD4+ and Treg." (PMID 34830435, 2021). "There was a trend toward increased proportion of CD14+ monocytes and decreased proportions of CD4+, CD8+ T cells, and NK cells in sepsis as compared to HC." (PMID 33828550, 2021). "A recent report in 2020 reported that IL-36 activated autophagy to ablating the immune inhibitory of CD4+CD25+ Treg, thus aggravating host immune response and the development of sepsis." (PMID 34845417, 2021).
Sepsis (continued). "Among the seven immune cell subsets investigated, proportions of CD14+ monocytes, CD4+ T cells, CD8+ T cells, mDCs, and NKs were significantly altered in sepsis compared to HC." (PMID 33828550, 2021). "These alterations indicated that both CD4+ and CD8+ T cell subsets were activated in the early stages of sepsis." (PMID 33717146, 2021). "The expression of early activation marker CD69 increased significantly at 12 h and then declined slowly on both CD4+ and CD8+ T cell subsets in AS mice, suggesting that both CD4+ and CD8+ T cell subsets were activated in the early stages of sepsis." (PMID 33717146, 2021). "We compared the mean fluorescence intensity (MFI) of CD69 and CD28 expression on gated CD4+ T and CD8+ T cells in the two sepsis models." (PMID 33717146, 2021). "Moreover, it is important to determine if the exacerbated exhaustion phenotype of CD4+ T cells in the RS mice is also seen in humans, due to the difference in immunological characteristics, comorbidities, and therapeutic targets between sepsis mice and patients." (PMID 33717146, 2021). "With regard to the critical role for CD4 T cells in EAE disease, the sepsis-induced lymphopenic state is known to impact both naive and memory CD4 T cells." (PMID 33191915, 2020). "The present study is to explore the effects of IL‐38 on CD4+CD25+Tregs and its beneficial action in sepsis." (PMID 31880383, 2020). "The present study took advantage of our ability to track the number and function of endogenous Ag-specific memory CD4 T cells in the wake of a septic event [using the cecal ligation and puncture (CLP) model of polymicrobial sepsis]." (PMID 32903436, 2020). "Both the absolute numbers of naïve T cells (CD4+CD45RA+; 82/μL (sepsis) versus 316/μL (control); * p < 0.05) and RTEs (CD31+CD4+CD45RA+; 29/μL (sepsis) versus 220/μL (control); p < 0.05) were significantly lower in patients with septic shock." (PMID 32825352, 2020). "Infiltration of multiple pro-inflammatory cells, such as macrophages and CD4+ T cells, is also commonly detected in the CLP sepsis model and the LPS-induced AKI model." (PMID 33287398, 2020). "Naturally occurring CD4+CD25+ regulatory T cells (Tregs) are required to limit immune‐induced pathology and to maintain homeostasis during the early‐phase of sepsis." (PMID 31880383, 2020). "Secondly, we determined the relative and absolute number of RTEs and their proliferative offspring by flow cytometric staining for CD31+CD4+CD45RA+ and CD31-CD4+CD45RA+ T-cells, respectively, in the peripheral blood of sepsis patients and controls." (PMID 32825352, 2020). "Activation of caspase-3 and externalization of phosphatidylserine in CD4+, CD8+, and CD19+ lymphocytes were reported in patients with sepsis." (PMID 32983116, 2020). "A seminal study by Chen al. showed significant upregulation of 2B4 on CD4 and CD8 T cells in human sepsis patients and in a CLP model of murine sepsis within 24 h of sepsis induction." (PMID 33613563, 2020). "Treatment with Ox40 agonistic Ab increased splenic CD4 T cell count, and surprisingly further augmented the CLP-induced increase in splenic myeloid cell (macrophages and monocytes) numbers at day 5 post sepsis." (PMID 33613563, 2020). "Just as seen with the 2W1S-specific memory CD4 T cells, CLP-induced sepsis led to a significant reduction in OVA323-specific memory CD4 T cell numbers and ability to produce IFNγ after in vivo restimulation." (PMID 32903436, 2020). "CTLA-4 acts to oppose CD28 which is a critical regulator of early T cell activation and proliferation, and CTLA-4 is found to be upregulated on CD4+, CD8+ and Tregs following sepsis." (PMID 33336293, 2020). "Clinical research has shown that overexpression of Fas caused excessive apoptosis of T cells and sharp drops in CD4+ T cells and the CD4+/CD8+ ratio in the peripheral blood in SAP, particularly when accompanied by sepsis." (PMID 32266154, 2020).
Sepsis (continued). "To better understand the cause for this reduced protection, we examined the impact of sepsis on the number and function of the OVA323-specific memory CD4 T cells." (PMID 32903436, 2020). "The present study demonstrated that PD-1 was upregulated on spleen CD4+ T cells and CD8+ T cells during sepsis, which represented the immunosuppressive state of CLP mice." (PMID 32719675, 2020). "Other reasons for not receiving the required dose of cisplatin include leucopoenia; dehydration; sepsis; poor ECOG; and a low CD4 count." (PMID 31216321, 2019). "The numerical reduction of multiple immune cell populations, including CD4 and CD8 T cells, is a major characteristic of the adaptive immune response after sepsis." (PMID 31844996, 2019). "Our data thus far have shown that the overall number of T lymphocytes as well as the CD4+ and CD8+ subpopulations including the naive T cells have largely returned to normal values 3.5 months after sepsis." (PMID 30730978, 2019). "Thymic output and the numbers of naive and effector/memory CD4+ and CD8+ lymphocytes quickly recovered after sepsis." (PMID 30730978, 2019). "The ratio of CD4 T cells to mononuclear cells in MLN and peripheral (inguinal) LNs (PLN) was diminished by sepsis, whereas the quantity of cells in SP or Peyer’s patches (PP) did not change significantly in either group of mice." (PMID 31323786, 2019). "In our study, we used in vitro stimulation and flow cytometry to examine Th1 and Th17 pathway activation in circulating naive, central memory, effector memory and terminally differentiated CD4+ and CD8+ T cells from sepsis patients and control subjects." (PMID 31658288, 2019). "Based on our results of the possible role played by mucosal DC-producing IL-1β during sepsis, we proposed a model to illustrate the compartmental differences DCs in systemic SP and mucosal MLN organs exert vis-à-vis CD4 T-cell proliferation." (PMID 31323786, 2019). "Furthermore IL-23 responsiveness of human CD8+ memory lymphocytes decreases with age, and there is lower potential for inducible CD4+/IL-23r with age and this decrease in Th-17 responsiveness with age could potentially contribute to the adverse sepsis outcomes observed in the elderly." (PMID 31658288, 2019). "Here, we further analyzed their coexpression on the same CD4+ and CD8+ T cells collected on the 5th day of sepsis." (PMID 31440257, 2019). "To evaluate the proportion of lymphocytes in late stage sepsis, we measured the proportion of CD4 and CD8 T cells in a murine sepsis model." (PMID 31844996, 2019). "Apoptotic death and depletion of CD4 and CD8 T cells and T cell exhaustion are hallmarks of patients with sepsis." (PMID 29944697, 2018). "Comparison of the expression levels as determined by percentage positivity of PD-1, PD-L1 and PD-L2 on CD4+ T cell subsets (CD27+ and CD27-) between patients with sepsis and healthy controls." (PMID 29661225, 2018). "Proportion of CD27+ B cells, CD27- B cells, CD27+ CD4+ T cells and CD27- CD4+ T cells that express PD-1, PD-L1 and PD-L2 in patients with sepsis compared to healthy controls." (PMID 29661225, 2018). "The decrease of CD4 T cell contents was observed at 12 h following CLP and continued to 3 days or longer after sepsis." (PMID 30052667, 2018). "CD43-/- septic mice exhibited a decrease in the frequency of IL-2+ CXCR3+ CD4+ cells relative to CD43-/- sham controls, suggesting a sepsis- related shift away from a Th1 phenotype." (PMID 30226896, 2018). "Comparison of expression of PD-1, PD-L1 and PD-L2 as determined by MFI on CD4+ T cell subsets (CD27+ and CD27-) between patients with sepsis and healthy controls." (PMID 29661225, 2018). "The novel findings from this pilot study include the first report of higher B cell expression of PD-1, PD-L1 and PD-L2 in sepsis, and differential expression of PD-1 by CD27 status in both B and CD4+ T cells." (PMID 29661225, 2018).